PPARG (peroxisome proliferator activated receptor gamma)
Diseases named in the same sentence as PPARG in open-access papers (continued):
Sharing a sentence is not in itself a finding about the gene and the disease.
Hyperglycemia (continued). "In our present study, we reveal that the traditional Chinese medication QLQX has a cardioprotective role in hyperglycemia-induced cardiomyocyte apoptosis via activating PPARγ in vitro." (PMID 34336956, 2021). "Gain and loss-of-function experiments identified a regulatory pathway in adipocytes involving miR-21a-3p, FGFR1, FGF21, and PPARγ that regulated adipocyte browning and participated in hyperglycemia-induced atrial fibrosis." (PMID 34484568, 2021). "Previously, we characterized pancreas-specific PPARγ KO mice that exhibited hyperglycemia and impaired glucose-induced insulin secretion." (PMID 34592314, 2021). "In our study, we revealed that QLQX inhibited hyperglycemia-induced cardiomyocyte apoptosis in NRCMs via activating PPARγ." (PMID 34336956, 2021). "The inhibition of this process would mediate the Peroxisome Proliferator Activated Receptor Gamma (PPAR-Y), which, by increasing the amount of glutathione, would prevent oxidative damage that is caused by the state of hyperglycemia." (PMID 33514002, 2021). "PPARγ activation directly induces alteration in glucose and lipid utilization, takes charge of hyperglycemia, and develops further beneficial influence." (PMID 34336956, 2021). "Consistent with the observation in NRCMs, in vivo, QLQX reversed the decreased expressions of PPARγ and PGC-1α which were caused by hyperglycemia-induced diabetic cardiomyopathy." (PMID 34336956, 2021). "Animal and human studies have shown that BPA induces adipocyte and hepatocyte PPARγ expression, leading to fasting hyperglycaemia and glucose intolerance." (PMID 33467592, 2021). "The same effect is obtained with the PPARγ agonist rosiglitazone, which increased PPARγ2 expression level and counteracted the hyperglycemia-induced enhancement of CB1 expression, inflammation, and glomerular fibrosis in diabetic animals." (PMID 33799988, 2021). "Here, in our study, we found that QLQX has a cardioprotective role in hyperglycemia-induced cardiomyocyte apoptosis via activating PPARγ in vitro." (PMID 34336956, 2021). "Type-2 diabetic animals supplemented with hesperidin improved hyperlipidemia and hyperglycemia and enhanced hepatic and adipocyte PPARγ protein expression." (PMID 32781523, 2020). "Another study suggested that chitosan oligosaccharide prevents hyperglycemia by inhibiting intestinal glucose digestion and transport and enhances glucose uptake, at least in part, by up regulating PPARγ expression of adiponectin in adipocytes." (PMID 33261597, 2020). "This drug has attracted the attention due to its multiple impressions beyond controlling hyperglycemia in liver, muscle, and adipose tissue by cell insulin-sensitizing activity and its effect on peroxisome proliferator-activated receptor-gamma (PPARγ)." (PMID 31508564, 2019). "Other researchers reported that cinnamaldehyde alleviated gestational hyperglycemia in rats through modulation of peroxisome proliferator-activated receptor gamma (PPARγ), pro-inflammatory cytokines and oxidative stress." (PMID 32133057, 2019). "Pioglitazone has been proven to protect retinal and/or choroidal cells from hyperglycemia-induced injuries in a PPARG-dependent pathway." (PMID 31915541, 2019). "In fact, they emphasized that PPARγ plays a vascular protective role against hyperglycemia-induced oxidative stress with the subsequent induction of HO-1 and upregulation of the Nrf2." (PMID 31470514, 2019). "The mRNA levels of RUNX2, PPARγ and AdipoQ were also correlated with adipogenesis, which shows chronic hyperglycemia favoring adipogenesis." (PMID 29988028, 2018). "The elevated C/EBPα and PPARγ expression and increased hyperglycemia in obese mice was ameliorated by the intake of fruits, vegetables, and edible seaweed and/or its derivatives." (PMID 28358328, 2017).
Hyperglycemia (continued). "The agonists of PPARγ have been widely applied for the management of hyperglycemia in T2DM by its effects on insulin sensitivity and serum adiponectin increase, and adipocyte differentiation induction that often results in weight gain." (PMID 28399925, 2017). "In conclusion, we demonstrated the down-regulation of PPARγ in both adipose and placenta tissues from GDM women, and we showed for the first time that expression of PPARγ in both adipose and placenta tissues was negatively correlated with hyperglycaemia." (PMID 29371958, 2017). "PPARγ activation is a therapeutic application that controls hyperglycemia and attenuates IR in type 2 DM." (PMID 25799429, 2015). "Treatment with BB at 30 mg/kg has been found to increase the cardiac level of PPARγ mRNA expression in a rat model of hyperglycemia and hypercholesterolemia." (PMID 26228038, 2015). "These are classified as PPARα and PPARγ activators and are used in hyperlipidemia and hyperglycemia treatments." (PMID 24885009, 2014). "PPARγ agonists, rosiglitazone and pioglitazone enhance insulin sensitivity, lower hyperglycemia and free fatty acid concentrations by improving glucose and lipid metabolism, improves adipokine profile and reduce adipose tissue inflammation." (PMID 25143786, 2014). "In contrast, PPARγ is present at higher concentrations in adipocytes, and PPARγ activation improves insulin sensitivity and reduces hyperglycemia." (PMID 24312343, 2013). "Peroxisome proliferator-activated receptor gamma (PPARγ) agonists are clinically used to counteract hyperglycemia." (PMID 23811337, 2013). "Thiazolidinediones (TZDs), among which Rosiglitazone, are known agonists of the peroxisome-proliferator-activated receptor γ (PPARγ) commonly used for treatment of hyperglycemia." (PMID 20613955, 2010). "Systemic activation of PPARγ in this study was evident by the reversal of hyperglycemia, increased serum adipocytokine adiponectin, and by weight gain in ZDF-treated rats." (PMID 19536350, 2009). "Agonists for both PPARα and PPARγ have been used to treat dyslipidemiaand hyperglycemia, respectively." (PMID 18769492, 2008). "Our working hypothesis is that the agonistic activity of MTX-531 against PPARγ counteracts PI3K-driven hyperglycemia." (PMID 38992135, 2024). "Activation of PPARγ by TZDs improves hyperglycemia and insulin sensitivity in patients with T2DM." (PMID 36836874, 2023). "However, the regulation of PPARγ activity and the downstream effects of PPARγ on hyperglycaemia-induced osteoporosis are still unclear." (PMID 36951483, 2023). "Further studies are necessary to precisely evaluate the correlation between gestational diabetes mellitus and PPARγ activity within the trophoblast and placenta, considering both the management of maternal hyperglycemia and related effects towards fetal growth." (PMID 38003402, 2023). "Our findings will expand treatment strategies for hyperglycaemia-induced osteoporosis and may also expand metformin treatment to other PPARγ-related diseases." (PMID 36951483, 2023). "In detail, treating diabetic mice with SGLT2i attenuated hyperglycaemia, dyslipidaemia, renal lipotoxicity, glomerular damage, and albuminuria, as well as increased renal PPARα and PPARγ with concurrent decreases in several inflammatory and oxidative stress markers." (PMID 38139208, 2023). "On the other hand, the PPARγ isoform primarily affects fatty acid synthesis, activates glucocorticoids, contributes to abnormal fatty acid metabolism, regulates triglyceride homeostasis, and mitigates hyperglycemia and hyperlipidemia damage." (PMID 37836471, 2023). "Hyperglycemia activates PPARγ pathways, thus decreasing the invasion of human CTB, followed by the increase of IL-6 and soluble fms-like tyrosine kinase-1 (sFIt-1) and the inhibition of urokinase plasminogen activator (uPA) and plasminogen activator inhibitor 1 (PAI-1)." (PMID 33406768, 2021).
Hyperglycemia (continued). "In summary, the present study demonstrates that in type-1 diabetic kidney, hyperglycemia results in the downregulation of PPARγ and the upregulation of RXRα, RXRβ and RARγ1, which possibly contributes to elevated PAI-1 levels, and thus, elevated MMP-9 and MMP-13." (PMID 34680110, 2021). "Earlier studies had verified that the down-regulation of peroxisome proliferator activated receptor gamma in placentas may predict hyperglycemia in offspring at young adulthood." (PMID 32184720, 2020). "Our in vitro experimental results demonstrated that rFGF21 is strongly protective in hyperglycemia plus IL-1β -induced transendothelial permeability, which is FGFR1 activation-dependent and PPARγ activity-dependent, and also associated with the maintenance of junction protein expression." (PMID 32012810, 2020). "In addition, hyperglycemia increases PPARγ synthesis by liver cells, which reverses the differentiation of macrophages from osteoclasts to adipocytes." (PMID 29552033, 2018). "However, in mice study, PPARγ expression was found to be up-regulated in placentas of diabetic pregnant mice with severe hyperglycaemia." (PMID 29371958, 2017). "The decreased expression of PPARγ was also observed in the patients with GDM, and this finding was consistent with previous reports showing down-regulation of placenta PPARγ expression under mild hyperglycaemia in GDM women and streptozotocin-induced diabetic rats." (PMID 29371958, 2017). "For hyperglycemia, the effect of modest variants in FOXO3 might be concealed by other major variants (e. g., PEPCK, PPARG and TCF7L2) in most studies based on middle-aged subjects." (PMID 25993007, 2015). "RXR agonists have also been shown to activate PPARα-inducible genes and lower triglycerides and raise HDL levels in vivo, reduce atherosclerosis in apoE knockout mice and activate RXR:PPARγ heterodimer to reduce hyperglycemia, hypertriglyceridemia and hyperinsulinemia." (PMID 25143786, 2014). "Considering to other components of MetS, there is not significant association between hyperglycemia and hypertension relative risk and PPARγ level." (PMID 24330836, 2013). "Overall, the here identified partial PPARγ activation pattern, in combination with suppression of hyperglycemia and weight gain, makes honokiol an interesting natural product with a good potential to be further explored as pharmaceutical lead or dietary supplement." (PMID 23811337, 2013). "To determine whether red clover extract attenuates hyperglycemia in diabetic mice by activating PPARγ, we analyzed the mRNA expression of PPARγ, glucokinase and CD36." (PMID 23170129, 2012). "It cannot be excluded that KATP channel blockers like repaglinide may affect oxidative/nitrosative stress but PPARγ agonists like pioglitazone seem to act more comprehensively which was confirmed independently on their action oh hyperglycemia." (PMID 22474428, 2012). "Since dual PPARα and PPARγ agonists might provide broader beneficial metabolic effects through a simultaneous treatment of hyperglycemia and dyslipidemia, compounds targeting both PPARα and γ have been developed by the pharmaceutical industry." (PMID 20981297, 2010). "In rodents TZD therapy results in a PPARG-mediated increase in new adipocytes of small size, potentially explaining the modest increase in body weight that paradoxically accompanies the reduction in hyperglycemia in humans." (PMID 20936101, 2010). "Furthermore, we explored whether PPARγ activation can alter the effect of metformin on hyperglycaemia-induced osteoporosis." (PMID 36951483, 2023). "Thus, PPARγ might be the downstream effector of QLQX in alleviating hyperglycemia-induced cardiomyocyte apoptosis." (PMID 34336956, 2021). "However, a pathway involved in PPARγ expression in hyperglycaemia was described." (PMID 20877467, 2010).
Hyperglycemia (continued). "Thus, to deal with bone impairment under hyperglycemia, it is important to take medicine on glycemic control to prevent fracture for diabetic patients except for TZDs treatment that had a side effect on the aggravation of bone fragility through upregulation of PPARγ." (PMID 36297386, 2022). "SMILE is a multifunctional transcription factor that reduces hyperglycemia induced by CREB/CRTC2 signaling and represses adipogenesis by regulating peroxisome proliferator-activated receptor γ (PPARγ)." (PMID 34211461, 2021). "Peroxisome proliferator-activated receptor gamma (PPAR-γ) agonists modulate glucose and lipid metabolism and are approved by FDA for the management of hyperglycemia and lipid disorders." (PMID 34881080, 2021). "It is very likely that beyond the suppression of hyperglycemia and the possible regulation of ACE2 expression, PPARγ agonists can demonstrate also another effect in COVID-19 patients." (PMID 32930095, 2020). "Pioglitazone is a peroxisome proliferator-activated receptor gamma (PPARγ) agonist belonging to the thiazolidinedione (TZD) class of drugs and used to treat hyperglycemia." (PMID 31541141, 2019). "Herein, we investigated the potential of a terpenoid rich fraction of the marine alga P. pavonia to ameliorate hyperglycemia, IR, hyperlipidemia, and oxidative stress in HFD/STZ-induced diabetic rats, pointing to the possible involvement of PPARγ." (PMID 31887984, 2019). "Moreover, hyperglycemia may utilize miR-34a-5p to induce some expression changes in PPARγ." (PMID 31398873, 2019). "As PPARγ is able to suppress GcG expression in mice, we suggest that the increased activation of PPARγ gene expression observed in the current study possibly leads to dysregulated GLP-1 secretion and, further, exacerbates hyperglycemia." (PMID 41614817, 2025). "Third, the blood concentration of rosiglitazone derived from oral administration while used for the treatment of hyperglycemia in humans does not guarantee a delivery of sufficient rosiglitazone to the colon for the activation of PPARγ locally." (PMID 37242462, 2023). "The results showed that metformin significantly reduced the expression of ERS-associated proteins, such as PERK, ATF4, and CHOP, in hyperglycaemic osteoblasts; downregulating PPARγ levels enhanced the effect of metformin on PERK, CHOP and ATF4 in the context of hyperglycemia." (PMID 36951483, 2023). "Determining whether PPARγ plays a protective role in the progression of GDM requires further in vivo studies, as systematic hyperglycemia may differ from that observed in in vitro models." (PMID 37299422, 2023). "In β-cells, hyperglycaemia-induced ERS is inhibited by metformin treatment and PPARγ activation." (PMID 36951483, 2023). "Our results showed that the downregulation of PPARγ in the diabetic kidney and HG-exposed MCs, corroborating previous findings; GYY treatment restored normal levels by reversing the effect of hyperglycemia and HG." (PMID 34680110, 2021). "Our in vitro experimental results also demonstrated that rFGF21 protects against hyperglycemia plus interleukin (IL)-1β-induced transendothelial permeability through upregulation of junction protein expression in an FGFR1 activation and PPARγ activity elevation-dependent manner." (PMID 32012810, 2020). "In addition, we investigated the potential of a terpenoid rich fraction of P. pavonia to ameliorate hyperglycemia, IR, and oxidative stress in a rat model of T2DM, pointing to the possible involvement of PPARγ." (PMID 31887984, 2019). "PPARγ agonists such as PIO function as insulin sensitizers that enhance insulin action, ameliorate hyperglycemia in T2DM, lower plasma free fatty acids and TG, modulate the expression of inflammatory cytokines and prevent excessive lipid accumulation in liver and other peripheral tissues." (PMID 31887984, 2019). "We identified honokiol as a partial non-adipogenic PPARγ agonist in vitro which prevented hyperglycemia and weight gain in vivo." (PMID 23811337, 2013).
Hyperglycemia (continued). "The severe β-cell phenotype of the POKO mouse contrasts with the absence of hyperglycaemia observed in the pancreatic β-cell specific PPARg KO mouse." (PMID 17465682, 2007). "We hypothesized that the absence of hyperglycemia in mice treated with MTX-531 stems from the molecule’s unique ability to act as an agonist of the nuclear hormone receptor PPARγ." (PMID 38992135, 2024). "Hyperglycemia following pancreatic β-cell injury through STZ treatment suppresses the expression of the transcription factor PPARγ, resulting in the cancellation of the inhibition of heparanase expression by PPARγ and the promotion of HS degradation on pancreatic islets by heparanase." (PMID 36292936, 2022). "Besides, the expressions of PPARγ and its coactivator PGC-1α were obviously decreased in the HG group, indicating that reduced PPARγ and PGC-1α might contribute to hyperglycemia-induced cardiomyocyte injury." (PMID 34336956, 2021). "However, even if insulin is quantitatively decreased in PPARγ-/F:MORE+/Cre pancreas this is unlikely to fully explain the inappropriately normal levels of circulating insulin observed in the presence of extreme hyperglycemia." (PMID 27505464, 2016). "In addition, Honokiol has been proved to be a partial nonadipogenic PPARγ agonist in vitro which prevented hyperglycemia and weight gain in diabetic KKAy mice." (PMID 26064877, 2015). "Indeed in aP2/DTA mice, whose white and brown fat is virtually eliminated by fat-specific expression of diphterin toxin A chain, TRO alleviated hyperglycemia without affecting PPARγ levels in liver, suggesting independence from both adipose tissue and PPARγ receptor." (PMID 20981297, 2010). "Given that PGC-1α acts as a transcriptional coactivator for PPARγ, thus regulating many physiological processes, we hypothesized that the downregulation of PGC-1α by glucose may play a role in an in vitro-model of VSMC proliferation and migration induced by hyperglycemia." (PMID 19142226, 2009). "Interestingly, studies have shown that the genetic deletion of PPARγ in the livers of lipodystrophic transgenic mice markedly attenuates the development of NAFLD, independent of the presence of hyperinsulinemia or hyperglycemia." (PMID 25892856, 2015).